LINC00690 (long independently transcribed non-coding RNA 690)
Gene: Long non-coding RNA gene on chromosome 3 (16,524,771 to 16,541,903, forward strand). Ensembl gene ENSG00000233570.
Diseases named in the same sentence as LINC00690 in open-access papers:
LINC00690 is named in the same sentence as 1 disease in open-access papers, as found by Europe PMC text mining. Sharing a sentence is not in itself a finding about the gene and the disease. The quoted sentences say what the papers report.
metabolic disorders (1 paper, 2021). "Our findings indicated that the downregulation of LINC00690 and the upregulation of RFTN1 played a key role in the metabolic disorders of PDC." (PMID 34926685, 2021).